CNOT8 (CCR4-NOT transcription complex subunit 8)
Description:
Has 3'-5' poly(A) exoribonuclease activity for synthetic poly(A) RNA substrate. Its function seems to be partially redundant with that of CNOT7. Catalytic component of the CCR4-NOT complex which is linked to various cellular processes including bulk mRNA degradation, miRNA-mediated repression, translational repression during translational initiation and general transcription regulation. During miRNA-mediated repression the complex also seems to act as translational repressor during translational initiation. Additional complex functions may be a consequence of its influence on mRNA expression. Associates with members of the BTG family such as TOB1 and BTG2 and is required for their anti-proliferative activity.
Synonyms: CALIF; POP2; CAF1; hCAF1; Caf1b
Tractability: PROTAC: ubiquitination databases record sites on it; its protein half-life has been measured.
Gene: Protein-coding gene on chromosome 5 (154,857,529 to 154,876,793, forward strand). Ensembl gene ENSG00000155508.
Subcellular location: Cytoplasm; Nucleus
Pathways (Reactome):
Developmental Biology: M-decay: degradation of maternal mRNAs by maternally stored factors
Metabolism of RNA: Deadenylation of mRNA
Gene Ontology:
Molecular function: 3'-5'-RNA exonuclease activity; poly(A)-specific ribonuclease activity; protein binding; nucleic acid binding
Biological process: miRNA-mediated gene silencing by mRNA destabilization; positive regulation of cell population proliferation; positive regulation of mRNA catabolic process; nuclear-transcribed mRNA poly(A) tail shortening
Cellular component: CCR4-NOT complex; nucleus; CCR4-NOT core complex; cytosol; P-body; cytoplasm
Genetic constraint (gnomAD): Loss-of-function variants: 12 observed, 25.05 expected, observed/expected ratio (o/e) 0.48, 90% interval 0.31 to 0.78. The upper end of that interval is the gene's LOEUF score, 0.78, which puts it in group 3 of 6, group 1 being the genes least tolerant of losing a copy. Missense variants: 158 observed, 309.11 expected, observed/expected ratio (o/e) 0.51, 90% interval 0.45 to 0.58. Synonymous variants: 86 observed, 108.09 expected, observed/expected ratio (o/e) 0.8, 90% interval 0.67 to 0.95.
Homologues: Orthologues: chimpanzee CNOT8 (100% identical), dog CNOT8 (100% identical), macaque CNOT8 (100% identical), pig CNOT8 (100% identical), rabbit CNOT8 (100% identical), guinea pig CNOT8 (99% identical), mouse Cnot8 (99% identical), rat Cnot8 (99% identical), tropical clawed frog cnot8 (91% identical), zebrafish cnot8 (83% identical), Drosophila melanogaster Pop2 (62% identical), Caenorhabditis elegans ccf-1 (45% identical). Paralogues in human: CNOT7 (74% identical).
Diseases named in the same sentence as CNOT8 in open-access papers:
CNOT8 is named in the same sentence as 23 diseases in open-access papers, as found by Europe PMC text mining. Sharing a sentence is not in itself a finding about the gene and the disease. The quoted sentences say what the papers report.
breast carcinoma (4 papers, 2021 to 2025). "To extend the previous analysis, we included data from silencing of CNOT6, CNOT6L, CNOT7, and CNOT8 from another cell line, namely, MCF7 (derived from pleural effusion of breast carcinoma), based on previous studies." (PMID 35630580, 2022). "CNOT7 and its paralog CNOT8 can influence the stability of cell cycle-related genes MSMB, PMP22, and Cyclin G2 through their deadenylation ability, promoting cell proliferation in breast cancer." (PMID 41249119, 2025).
cataract (1 paper, 2025). Partial or complete opacity of the crystalline lens of one or both eyes that decreases visual acuity and eventually results in blindness. "Reassuringly, as part of this study we identified several gene pairs such as SLC25A37/SLC25A28 and CNOT7/CNOT8 that represent attractive targets for further drug development, with Slc25a28 knockout mice being viable and fertile with no overt phenotypes, other than cataracts in some mice." (PMID 40968372, 2025).
lung adenocarcinoma (1 paper, 2024). A carcinoma that arises from the lung and is characterized by the presence of malignant glandular epithelial cells. "Likewise, CNOT8 protein levels were inversely correlated with CNOT7 copy numbers in patients with lung adenocarcinoma (LUAD) and BRCA in the NCI Clinical Proteomic Tumor Analysis Consortium cohort." (PMID 39009815, 2024).
metastatic disease (1 paper, 2016). "In contrast Cnot8 suppressed both primary tumor growth and metastatic disease, suggesting a more general role in regulating tumor cell proliferation." (PMID 26807845, 2016). "The integrated genetics and gene expression analysis that initially identified Cnot2 also implicated other genes associated with RNA deadenylation (Cnot8, Angel2, Tob1) as potential modulators of metastatic disease, suggesting that this function of CCR4-NOT might be a critical determinant." (PMID 26807845, 2016).
tumor (10 papers, 2016 to 2025). "For several genes, most notably CNOT7, GDI1 and SLC25A37, there are a subset of tumours that showed homozygous deletion and thus inhibition/suppression of CNOT8, GDI2 or SLC25A28, respectively, would be predicted to provoke cellular lethality/reduced cancer cell fitness." (PMID 40968372, 2025). "We therefore selected Cnot8 and its highly conserved paralog Cnot7 to determine whether the deadenylation function of CCR4-NOT plays a critical role in tumor progression." (PMID 26807845, 2016).
cancer (6 papers, 2014 to 2025). A tumor composed of atypical neoplastic, often pleomorphic cells that invade other tissues. "It remains to be investigated how CNOT7 and CNOT8 contribute to the development and progression of cancer." (PMID 25191340, 2014). "There are some reports that CNOT7 and CNOT8 are relevant to the development and progression of cancer." (PMID 25191340, 2014).
CNOT8 also shares sentences with these, for which no sentence is quoted: dental caries (2 papers); adenocarcinoma (1); adenoma (1); colonic tumors (1); gastric cancer (1); inflammatory bowel disease (1); inflammatory breast carcinoma (1); intestinal inflammation (1); lymph node metastasis (1); lymphoma (1); male infertility (1); osteoporosis (1); ovarian carcinoma (1); pancreatic cancer (1); Pleural effusion (1); renal carcinoma (1); signet ring cell carcinoma (1).